NCOR1 (nuclear receptor corepressor 1)
Diseases named in the same sentence as NCOR1 in open-access papers (continued):
Sharing a sentence is not in itself a finding about the gene and the disease.
abdominal aortic aneurysm (1 paper, 2026). Enlargement and ballooning of the vessel that supplies arterial blood to the abdomen, pelvis and legs. "While NCOR1 has already been linked to vascular biology, its relevance in abdominal aortic aneurysm (AAA) remains unclear, particularly for NCOR2." (PMID 42072455, 2026).
Anxiety (1 paper, 2020). Intense feelings of nervousness, tension, or panic often arise in response to interpersonal stresses. "Injection of siRNA targeting NCOR1 into the amygdala of rats at 12 or 28 hours after birth reveals that NCOR1 knockdown increases juvenile social play behaviors in males and anxiety-like behaviors in both males and females." (PMID 32449767, 2020).
apraxia (1 paper, 2016). Apraxia is a neurological disorder characterized by the inability to perform tasks or movements, despite having the desire and physical ability to perform them. "DECIPHER lists 20 syndromic cases with CNVs involving NCOR1 including one with truncal ataxia, one with apraxia, and one with delayed speech and language development." (PMID 27120335, 2016).
asthma (1 paper, 2023). "In conclusion, macrophage NCOR1 deficiency promoted the regulation of M2 programming by enhancing PPARγ expression to exacerbate asthma." (PMID 38030614, 2023). "In the present investigation, we demonstrated that NCOR1 deficiency in macrophages aggravated OVA-induced asthma." (PMID 38030614, 2023). "Collectively, these results demonstrated that macrophage NCOR1 deficiency exacerbated Th2 cytokine production in the progression of asthma." (PMID 38030614, 2023). "We used ovalbumin (OVA) to induce macrophage NCOR1-deficient mice for asthma formation." (PMID 38030614, 2023). "Collectively, these data suggested that macrophage NCOR1 deficiency exacerbated asthma in mice." (PMID 38030614, 2023). "Interestingly, our results suggested that M2 macrophage polarization was promoted in MNKO mice, suggesting that macrophage NCOR1 deficiency might exacerbate asthma by enhancing M0 to M2 polarization." (PMID 38030614, 2023). "The results of the current study identified that NCOR1 depletion in macrophages disrupted the pulmonary immune system during the development of asthma." (PMID 38030614, 2023). "Mechanistic studies suggested that NCOR1 promoted macrophage polarization by interacting with PPARγ, contributing to the pathogenesis of asthma." (PMID 38030614, 2023). "The aim of this research was to examine the role and mechanism of macrophage NCOR1 in the development of asthma." (PMID 38030614, 2023). "The next question to be addressed is to find the pathway by which NCOR1 in macrophages regulates M2 programming and thus exacerbates asthma." (PMID 38030614, 2023). "In summary, NCOR1 suppresses the inflammatory response during asthma development by regulating macrophage polarization." (PMID 38030614, 2023). "MNKO mice were used to investigate the effect of macrophage NCOR1 deletion on inflammation and macrophage differentiation in asthma." (PMID 38030614, 2023). "Therefore, we intended to investigate the involvement of macrophage NCOR1 in asthma." (PMID 38030614, 2023). "Macrophage NCOR1 might be a potential target for the treatment of asthma." (PMID 38030614, 2023). "In a mouse model of asthma induced by OVA peptides, the protein level of NCOR1 was significantly decreased in the lung tissues of asthmatic mice compared with control mice." (PMID 38030614, 2023).
Cirrhosis (1 paper, 2024). A chronic disorder of the liver in which liver tissue becomes scarred and is partially replaced by regenerative nodules and fibrotic tissue resulting in loss of liver function. "Furthermore, we observed upregulated regulon activities for NCOR1, a frequently mutated gene, in stem-like cells of both cirrhosis and HCC, showing increased expressions along malignant progression." (PMID 38645221, 2024).
congenital heart disease (1 paper, 2019). A heart disease that is present at birth. "Although human studies have identified NCoR1 as a candidate gene for pathogenesis of left‐sided congenital heart disease, the exact functions of NCoR1 during cardiac development and disease have not been explored." (PMID 31532577, 2019).
dysplasia (1 paper, 2008). A usually neoplastic transformation of the cell, associated with altered architectural tissue patterns. "We observed greater than 300% increase in NCOR1 in severe and mild/moderate dysplasia relative to normal suggesting an increase in NCOR1 occurs very early in disease development (CIN II/CIN I)." (PMID 18248679, 2008).
familial renal glucosuria (1 paper, 2020). Familial Renal Glucosuria (FRG) is characterized by the presence of persistent isolated glucosuria in the absence of both generalized proximal tubular dysfunction and hyperglycemia. "In conclusion, WES identified DNA variants in four different genes as potential novel causes of IKH, suggesting that IKH is a heterogeneous disorder that can be split into several novel diseases: NCOR1-KH, IGF2BP1-KH, SGLT2-KH or familial renal glucosuria KH, and NEK11-KH." (PMID 32034166, 2020).
head and neck cancer (1 paper, 2019). A primary or metastatic malignant neoplasm affecting the head and neck. "Relatively frequent mutations were also detected in several other IntOgen-defined cancer drivers such as MGA, PABPC3, NR4A2, NCOR1 and MACF1; of these PABPC3, NR4A2, NCOR1 and MACF1 are detected as mutational cancer drivers in head and neck cancer in IntOgen." (PMID 31427592, 2019).
hyperandrogenemia (1 paper, 2021). "The abnormal DNA methylation of estrogen and androgen synthesis-related genes (such as NCOR1, PPARG1, HDAC3, and CYP19A1) is believed to be a major factor underlying the development of hyperandrogenemia in PCOS." (PMID 33763111, 2021).
Infertility (1 paper, 2024). "With this context, the identification of VDR, NCOR1, and SMAD3 in this study must be evaluated further to explore their role in therapies for VD-deficient females with infertility." (PMID 38586664, 2024).
intestinal polyposis (1 paper, 2021). "In conclusion, depletion of NCOR1 reduced intestinal polyposis in mice and caused growth arrest, leading to senescence in human colorectal cell lines." (PMID 34503224, 2021).
ischemic stroke (1 paper, 2023). A stroke disorder caused by obstruction of blood flow to the brain, due to thrombotic (local blood clot formation) or embolic (due to a blood clot or other material traveling from another site) event. "For example, NCOR1 interacts with LXRβ in microglia, and knockdown of NCOR1 in macrophages protects against ischemic stroke." (PMID 38030614, 2023).
lupus (1 paper, 2024). "Moreover, crucial transcriptional regulators related to lupus such as HDACs/Sin3A, cAMP-responsive element-binding protein (CREB), and nuclear receptor corepressor 1 (NCoR1) were upregulated in both B6.Mecp2Tg1 and MRL/lpr when compared to B6 controls." (PMID 38524134, 2024).
muscle atrophy (1 paper, 2022). The loss of muscle tissue due to inactivity or disease. "A study showed that TJ-41 downregulated nuclear receptor corepressor 1 (NCoR1) expression, and induced muscle differentiation and metabolism by regulating NCoR1associated gene expression in weightlessness-induced muscle atrophy." (PMID 36578084, 2022).
Mycobacterium infection (1 paper, 2023). Infections with bacteria of the genus Mycobacterium. "Increased expression of NCoR1 in myeloid cells during the early stage of Mycobacterium infection demonstrated its importance for the control of host defence against infection." (PMID 37590294, 2023). "To identify the role of AMPK/mTOR signalling culminating into dysregulated autophagy in NCoR1 KD mo-MΦ upon mycobacterial infection, we treated the cells with metformin, an AMPK activator." (PMID 37590294, 2023). "NCoR1 KD mo-MΦ showed lower AMPK activity at 2 h and 24 h post Mycobacterium infection, which is consistent with the mTOR activity." (PMID 37590294, 2023).
periodontitis (1 paper, 2023). An acute or chronic inflammatory process that affects the tissues that surround and support the teeth. "Deficiency of Ncor1 in macrophages exacerbates periodontitis by regulating Cebpα transcription through PPARγ, promoting osteoclastogenesis and neutrophil accumulation in mice with experimental periodontitis." (PMID 38030614, 2023).
polyp (1 paper, 2021). A usually exophytic mass attached to the underlying tissue by a broad base or a thin stalk. "Overall, these observations supported that abrogation of intestinal epithelial NCOR1 expression reduced initiation of intestinal neoplasia under the ApcMin/+ background without affecting polyp growth." (PMID 34503224, 2021).
polyposis (1 paper, 2021). "Conditional intestinal epithelial deletion of Ncor1 in ApcMin/+ mice resulted in a significant reduction in polyposis." (PMID 34503224, 2021).
prostate tumor (1 paper, 2013). "That study found NCoR1 to have diagnostic and prognostic significance in prostate tumor samples via antagonizing PPARα/γ signaling." (PMID 23669876, 2013).
sarcoma (1 paper, 2022). A usually aggressive malignant neoplasm of the soft tissue or bone. "If amplification of NCOR1 correlates with increased protein levels in these sarcomas, which RNA sequencing data suggests it may, this could lead to altered differentiation and transcriptional programs." (PMID 35705560, 2022).
Stroke (1 paper, 2020). Sudden impairment of blood flow to a part of the brain due to occlusion or rupture of an artery to the brain. "R1 includes genes and their products involved in circadian rhythms, while its major hub NCOR1 in macrophages blocks the pro-atherogenic functions of peroxisome proliferator-activated receptor gamma (PPARγ) (Oppiet al., 2020), greatly implicating stroke pathophysiology." (PMID 33224479, 2020).
thyroid (1 paper, 2013). "The findings that Cdkn1A and Bax mRNA were higher in the thyroid of ThrbPV/PVNcor1ΔID/ΔID than ThrbPV/PVNcor1+/+ mice provided us with a tool to further investigate the mechanisms by which NCOR1 regulated thyroid carcinogenesis." (PMID 23840792, 2013). "Therefore, NCOR1 acts in dual modes on the oncogenic actions of PV via nuclear and extranuclear actions to affect thyroid carcinogenesis of ThrbPV/PV mice." (PMID 23840792, 2013).
thyroid tumor (1 paper, 2021). A benign or malignant neoplasm affecting the thyroid gland. "It has been suggested that NCOR1, via protein–protein interaction, is a novel regulator of PI3K signaling and could modulate thyroid tumor progression." (PMID 34680332, 2021).
triple-negative breast carcinoma (1 paper, 2024). An invasive breast carcinoma which is negative for expression of estrogen receptor (ER), progesterone receptor (PR), and human epidermal growth factor receptor 2 (HER2). "Previous studies have reported a significantly higher mutation frequency of NCOR1 in triple-negative breast cancer cases among white populations compared to black populations." (PMID 39541191, 2024).
tuberculosis (1 paper, 2023). A chronic, recurrent infection caused by the bacterium Mycobacterium tuberculosis. "When we compared individuals with active tuberculosis to healthy controls, we found that the expression of the NCOR1 transcript was significantly lower in the active TB cases." (PMID 37590294, 2023).
cancer (86 papers, 2008 to 2025). A tumor composed of atypical neoplastic, often pleomorphic cells that invade other tissues. "Although previous studies have shown that CMA can degrade NCoR1 in various cancer cells, little is known about the mechanisms underlying CMA inhibition-mediated lipid accumulation." (PMID 37524243, 2023). "NCOR1 is located on chromosome 17p11.2., in an area that is frequently mutated or lost in several human cancers." (PMID 34503224, 2021). "Missense mutations were recognized in Ncor1 and Pik3ca, oncogenes of central importance to human cancer as known driver mutations." (PMID 29925311, 2018). "To do so, we used the cancer genomics database cBioportal to identify NCOR1 mutations in each METABRIC patient." (PMID 30485330, 2018). "Additional database interrogation revealed that the updated MAF of this NCOR1 variant is 43%, according to the Exome Aggregation Consortium and is reported in only 0.07% of all cancers in COSMIC." (PMID 29254223, 2017). "It contains 10 genes with correlated expression level change, including four with prior association with cancer (NCOR1, FLCN, PEMT and PTRH2)." (PMID 24670534, 2014). "Some studies associate loss of expression of NCOR1 with cancer propagation and proliferation." (PMID 30485330, 2018). "While these association studies raised the possibility that NCOR1 could act to affect cancer progression, direct evidence of its roles in carcinogenesis in vivo is still lacking." (PMID 23840792, 2013). "There are some indications that NCOR1 dysfunction may be associated with cancer." (PMID 34503224, 2021). "Additional evaluation of data generated by the TCGA Research Network revealed an overall increase in the NCoR1/RARα ratio correlating to increasing CMA score between cancer types." (PMID 40490560, 2025). "The discovery of six amplified (i.e., WHSC1L1, CCND1, and SOX2) and 29 deleted (i.e., NCOR1, SETD2, and CBL) cancer associated genes was highlighted." (PMID 38539567, 2024). "Identifying a number of putative drivers, ARID1A, CHD4, HCFC1, STAG2, SMARCA4, and NCOR1 are known cancer driver genes." (PMID 37444571, 2023). "The NGS analyses identified mutations in eight cancer associated genes: ESR1, MECOM, JAK3, KMT2C, CTNNB1, CALR, NCOR1 and AMER." (PMID 34209696, 2021). "That indicated collapse of the mitochondrial membrane potential and eventually apoptosis, suggesting the potential role of NCOR1 as suppressor in cancer progression." (PMID 33058520, 2020). "Among genes shared with BC and NTC/NCC lineage cancers, in this study, NCOR1 was an important discovery." (PMID 26246470, 2015). "Mutational inactivation of inhibitory factors NCOR1, NCOR1 and NRIP1, and activating changes in NCOA1, NCOA2 and TNK2 are observed in primary cancers but are much more frequent in metastatic." (PMID 25277175, 2014). "The availability of a mouse model that spontaneously develops metastatic follicular thyroid cancer (FTC) provided us with a powerful tool to assess the role of NCOR1 in cancer development and progression." (PMID 23840792, 2013). "This prompted us to investigate whether cancer cells may also use the RARα/NCoR1 axis to sustain their elevated CMA activity." (PMID 40490560, 2025). "Furthermore, NCoR1 KD in cancer cells resulted in significantly reduced CMA activity (efficiency of KD is shown in Fig. EV2D)." (PMID 40490560, 2025).
cancer (continued). "“Transcriptional misregulation dysregulation in cancer” shows genes such as NCOR1 and MDM2." (PMID 40621499, 2025). "The lower expression of LATS1 and NCOR1 in basal-like cancers suggests that luminal tumors with diminished levels of either protein might be more susceptible to adopting basal-like attributes." (PMID 36443319, 2022). "Indeed, the role of NCOR1 in cell proliferation and cancer development has been described in previous reports, and our data showed that NCOR1 knockdown selectively suppressed the proliferation of ERα-positive cells in vitro and tumor growth in vivo." (PMID 34073371, 2021). "Thus, we expected that TNFα treatment or NCOR1 knockdown contributed to overcoming tamoxifen tolerance by increasing the sensitivity of cancer cells to this drug." (PMID 34073371, 2021). "Bioinformatics analysis revealed that SNPs in six genes (NCOR1, GATA3, CDH1, ATM, AKT1, and PTEN) were significantly associated with the corresponding expression levels and were involved in multiple pathways involved in cancer development." (PMID 30883028, 2019). "Mutations in six genes (NCOR1, GATA3, CDH1, ATM, AKT1, and PTEN) were significantly correlated with the corresponding expression levels, and were enriched and involved in multiple cancer‐related pathways." (PMID 30883028, 2019). "Interestingly, recurrent mutations of genes previously reported to be mutated in cancer: ABL1, BUB1B, NCOR1 (each mutated in three tumours), and CARS, HSP90AB1, NCOA1 (each mutated in two tumours) were uniquely found in recurrent/metastatic NPCs (n=33)." (PMID 28098136, 2017). "A number of studies have suggested that NCOR1 plays an important role in human cancers." (PMID 27788148, 2016). "In conclusion, these observations suggest that the Siah2/NCoR1 axis may be an attractive target for the treatment of metabolic diseases and several types of cancers." (PMID 26832397, 2016). "Hitting these cells with a drug that further decreases oxidative metabolism may limit cell growth and contribute to the survival benefit observed in patients with high NCoR1 levels in their cancer cells." (PMID 26832397, 2016). "More importantly 9 new cancer genes were identified; seven of them (ARID1B, CASP8, MAP3K1, MAP3K13, NCOR1, SMARCD1, CDKN1B) carried truncating mutations and were characterized by biallelic inactivation, suggesting that they were potentially recessive cancer susceptibility genes." (PMID 26561834, 2015). "Studies have suggested that the nuclear receptor corepressor 1 (NCOR1) could play an important role in human cancers." (PMID 23840792, 2013). "Transcriptional profiling of such a large cohort of a single molecular type of cancer allows for a thorough understanding of the tumor’s genomic landscape, including the identification of genes affected by mutations (GNAS, MYCN, PPM1D, and PRKAR1A), and fusion transcripts (ZBTB20 and NCOR1)." (PMID 33741928, 2021). "Two proteins in this complex, NCOR1 and TBL1XR1, had been previously reported as cancer driver genes and shown to regulate key signalling pathways in modulating tumour growth." (PMID 40205054, 2025). "The correlation between the NCoR1/RARα ratio and CMA score is additionally observed when comparing individual patients in most cancers (Fig. EV7C)." (PMID 40490560, 2025). "The distribution patterns of several known cancer driver genes, including CTNNB1, ATM, CHEK2, and NCOR1, exhibit racial disparities across datasets." (PMID 39541191, 2024). "HDAC3, the unique HDAC isoform that binds to the nuclear receptor corepressor NCOR1/SMRT, has been revealed to play a specific role in the emergence and development of cancer." (PMID 35910736, 2022).